TFF1 (trefoil factor 1)
Diseases named in the same sentence as TFF1 in open-access papers (continued):
Sharing a sentence is not in itself a finding about the gene and the disease.
tumor (continued). "The gastric tumour suppressor trefoil protein TFF1 is present as a covalently bound heterodimer with a previously uncharacterised protein, TFIZ1, in normal human gastric mucosa." (PMID 18722547, 2009). "Our recent study highlights the role of the inflammatory microenvironment, particularly IFNγ signaling, in driving the silencing of TFF1, a well-established tumor suppressor in gastric carcinogenesis, with the transcription factor C/EBPβ playing a key role in this process." (PMID 41573568, 2025). "AGR2, FXYD3, TFF1, and MUC13 are associated with increased tumor grade." (PMID 39682235, 2024). "Given that TFF1 is expressed in a broad range of tumor entities, TFF1 IHC may have only limited utility for the discrimination of different tumor entities." (PMID 39410561, 2024). "Ki67 and TUNEL assays confirmed the role of TFF1 in regulating tumor growth and cell death." (PMID 39539551, 2024). "Although we found that TFF1 functions as a tumor suppressor in pancreatic premalignant lesions, it is unclear whether it has the same function in mature malignant tumors in vivo." (PMID 38872370, 2024). "TFF1, present in gastric mucus, may be related to the growth and spread of tumors and a favorable tumor prognosis." (PMID 37702857, 2023). "All patients with TFF1-positive AH also expressed TFF1 in the original tumor." (PMID 37835522, 2023). "Similarly, the tumor with the second-highest AH TFF1 concentration (T33) displayed a reduction to zero after only two therapy cycles." (PMID 37835522, 2023). "The quantitative real-time polymerase chain reaction (qRT-PCR)-derived “ER gene (ER-ness) score” for the expression of the ESR1 gene and downstream gene targets (ESR1, GATA3, TFF1) was confirmed to be an accurate predictor of the ER status in ER low-status tumor samples." (PMID 36834918, 2023). "Our group demonstrated that TFF1 correlates with a higher clinical tumor-node-metastasis (TNM) stage and poorly differentiated tumor cells and a recent study showed that TFF1 is linked to RBs which are associated with a higher risk of metastasis, referred to as subtype 2." (PMID 35158945, 2022). "We could show that RB tumor cells indeed secrete measurable amounts of soluble TFF1 into the aqueous humor of RB patients’ eyes." (PMID 35158945, 2022). "Therefore, soluble TFF1 is potentially secreted from the tumor cells into the aqueous humor of RB patients." (PMID 35158945, 2022). "Additionally, we compared the TFF1 status of the corresponding RB primary cell culture cells with TFF1 levels in the tumor of origin." (PMID 35158945, 2022). "Our results support a tumor-suppressor role of TFF1 in human CRC, and we suggest that TFF1 could be used for CRC detection and as a novel therapeutic target in L1-mediated CRC." (PMID 36139637, 2022). "Here, Tff1 peptide seems to play a role as a tumor suppressor." (PMID 35628183, 2022). "Identifying TFF1 as a tumor suppressor in CRC cells could provide a novel marker for L1-mediated CRC development and a potential target for therapy." (PMID 36139637, 2022). "In addition, we found out that the proliferative ability was suppressed followed by the mutation of TFF1-MS and TFF2-MS in tumor cells." (PMID 36428568, 2022). "It seems, however, that not all TFF1-positive RB tumors can be identified by AH sampling, probably due to a lower secreting rate of some TFF1-positive RB tumors or fewer TFF1-positive cells within the tumor bulk resulting in TFF1 concentrations in AH samples that are below the detection limit." (PMID 35158945, 2022). "In combination with other factors (genetic, environmental and nutritional), the pro-inflammatory response may trigger pro-oncogenic mechanisms that lead to the silencing of tumour-suppressor genes, such as trefoil factor 1 (TFF1)." (PMID 36514982, 2022).
tumor (continued). "Here, we analyse the molecular mechanisms involved in silencing TFF1, one of the protective and tumour-suppressing genes, in the context of the chronic inflammation triggered by H. pylori infection, focusing on the role of IFNγ, one of the major cytokines expressed during this inflammatory response." (PMID 36514982, 2022). "Some human studies showed that TFF1 can protect mucosa against damage and suppress carcinogenesis, while other studies showed that TFF1 can restrict cell adhesion, promote tumor cell invasion, and block necrosis of tumor cells." (PMID 34679875, 2021). "Circ-TFF1 could promote BC cell proliferation, migration, invasion, and epithelial-mesenchymal transition (EMT) in vitro and facilitate tumor growth in vivo via sponging miR-326 to increase TFF1 expression." (PMID 33777954, 2021). "Moreover, TFF1 and PgR have both been identified as biomarkers of a better prognosis in ER + tumours." (PMID 34453638, 2021). "In conclusion, the present study revealed a significant reduction in the expression of TFF1 in GCs when compared with GPs and normal gastric mucosa, which suggests that TFF1 may act as a tumor suppressor during canine gastric carcinogenesis." (PMID 34679875, 2021). "We therefore analysed the expression of the ER-regulated genes (ERGs) TFF1, GREB1 and PR, together with PLK1, Ki67, PCNA and CENPE (a centromere associated protein that accumulates in G2 phase and is involved in chromosome alignement), in treated tumours." (PMID 32792481, 2020). "Another tumor suppressor that is negatively affected by H. pylori is TFF1 (trefoil factor 1)." (PMID 31611869, 2019). "Additionally, TFF1 has been found to inhibit the occurrence and development of tumours as a tumour suppressor." (PMID 31455213, 2019). "TFF1 is involved in inhibition of tumour invasion and migration, and it may be used as a target to enhance the chemotherapy sensitivity by regulating apoptosis resistance." (PMID 30612555, 2019). "A previous study has shown that a combination of the progestin medroxyprogesterone acetate (MPA) and the Ras inhibitor S-farnesylthiosalicylic acid (FTS, also known as Salirasib) inhibited tumor growth and enhanced type 2 EC cell death by reducing expression of ER-target genes, including TFF1." (PMID 29682207, 2018). "Interestingly, our data shows that TFF1 expression levels are capable of discriminating esophageal mucosa from healthy individuals from histologically normal tumor surrounding tissue with 92.3% of accuracy." (PMID 29296124, 2017). "In addition, TFF1 protein was undetectable both in tumor and surrounding mucosa by immunohistochemistry, while submucosa glands of the healthy esophagus showed positive staining." (PMID 29296124, 2017). "TFF1 is classified as a tumor suppressor gene in gastric and may have a similar role in other tumor types." (PMID 29296124, 2017). "Similarly, TFF1-KO also enhances tumor formation in ovary and lung using a 7,12-dimethylbenz[a]anthracene (DMBA)-induced carcinogenesis model." (PMID 29296124, 2017). "Interestingly, TFF1 expression was capable of distinguishing tumor surrounding normal tissue from normal mucosa of healthy individuals with 92% accuracy." (PMID 29296124, 2017). "Deregulation of pathways that sustain C/EBPβ functions, such as inflammatory signals, may enhance proliferation and repression of differentiation genes, such as TFF1, that ultimately promotes tumor development." (PMID 27522676, 2016). "Interestingly, vorinostat treatment resulted in decreased gene expression of both TFF1 and PR, despite having minimal impact on tumor growth." (PMID 27472462, 2016). "Field effects for DNA methylation changes in RASSF1, EGFR and TFF1 might be important in influencing pre-neoplastic changes in gene expression relevant to tumor development." (PMID 26510686, 2015). "TFF1 has been reported to be a tumor suppressor in gastric epithelial cells." (PMID 25015107, 2014).
tumor (continued). "The mechanisms by which TFF1 might exert its tumor suppressor functions and promote cell death remain largely unrecognized." (PMID 25015107, 2014). "Indeed, MNU treatment in mice affects the expression of TFF1, an important gastric-specific tumor suppressor gene, through epigenetic modifications." (PMID 24216700, 2013). "It has been suggested that TFF1 may be involved in tumour dissemination because it stimulates migration and invasion of tumour cells." (PMID 18722547, 2009). "Loss of or weak TFF1 expression in the main tumour mass was contrasted frequently with strong expression of TFF1 but not TFIZ1 by carcinoma cells at the infiltrating edge or disseminated through the submucosa." (PMID 18722547, 2009). "In seeming contradiction to its proposed role as a tumour suppressor, TFF1 is frequently over-expressed or expressed ectopically by tumour cells (May and Westley, 1997)." (PMID 18722547, 2009). "In the longer term, persistence of the imbalance in TFIZ1 and TFF1 expression could increase the invasive behaviour of any tumour induced." (PMID 18722547, 2009). "This may have biological implications as it is known that the TFF1 dimer stimulates the migration of tumour cells." (PMID 18722547, 2009). "TFFs are also found in many cancers, and TFF1 knock-out mice exhibit tumor increasing, indicating that it may be a specific tumor suppressor gene for stomach." (PMID 18335045, 2008). "However, the reported frequencies of TFF1 positivity vary considerably for most tumor types." (PMID 39410561, 2024). "Furthermore, we immortalized cells of a RB1 mutated, MYCN amplified and trefoil factor family peptid 1 (TFF1) positive RB tumor and RB derived non-tumor stromal tissue." (PMID 39695086, 2024). "Additionally, we found one tumor (T38) with moderate levels of TFF1 secretion." (PMID 37835522, 2023). "Overall, E2 levels were significantly positively correlated with tumor enrichment in the hallmark estrogen response pathway (red bars) and with the expression of genes demonstrated to be transcriptionally regulated by ER (BCL2, IGF1R, GATA3, PIK3CA) and ligand-dependent ER (ESR1, XBP1, TFF1)." (PMID 36428742, 2022). "Thus, the function of Tff1 as a tumor suppressor clearly shows a gene dose effect." (PMID 35628183, 2022). "Thus, it has been proposed that TFF1 functions as a gastric tumor suppressor gene." (PMID 34679875, 2021). "Trefoil factor 1 might contribute to the tumor suppressing effects of GKN2." (PMID 31382983, 2019). "Moreover, high levels of TFF1 were observed in different tumor tissues (colonic, pancreatic, and ovarian), in comparison with normal counterparts, correlated with the stimulation of cell survival, migration, invasiveness, and tumor dissemination." (PMID 29997345, 2018). "Since the reduction of TFF1 expression was already observed in histologically normal tumor surrounding cells, we evaluated if TFF1 mRNA expression could distinguish esophageal mucosa from healthy individuals from histologically normal surrounding tissue from ESCC patients." (PMID 29296124, 2017). "Taken together, our results suggest that a TFF1 promoter methylation increase of less than 20% can result in a reduction of gene expression greater than 80% and total absence of protein expression, as observed when comparing healthy esophagus and non-tumor adjacent mucosa from ESCC patients." (PMID 29296124, 2017). "To investigate whether TFF1 inhibits tumor growth in vivo, we used a xenografting mouse model." (PMID 25015107, 2014). "This panel of genes includes trefoil factor family proteins, TFF1 and TFF3, which have been shown to be upregulated in BL immunohistochemistry tumor samples from patients with HR+/HER2- mBC who experience late progression on CDK4/6i therapy." (PMID 39955556, 2025). "Subcutaneous tumors formed in mice injected with TFF1-knockdown LEWIS cells were significantly smaller than those in the control group, and the tumor weight was also markedly reduced." (PMID 39539551, 2024).
tumor (continued). "Knockdown of TFF1 significantly inhibited LUAD cell proliferation, induced apoptosis, and suppressed in vivo tumor growth." (PMID 39539551, 2024). "Exemplary immunohistochemical stains of RB patient tumor sections revealed that TFF1+ tumors are also positive for GIPR, whereas TFF1-tumors also stain negatively for GIPR." (PMID 38730608, 2024). "In the established subcutaneous tumor model in C57BL/6 mice, we further evaluated the impact of TFF1 knockdown on tumor growth." (PMID 39539551, 2024). "Specifically, expression levels of BCL2, SLC40A1, and TFF1 were decreased in BCa samples with respect to normal tissues, whereas APOOL and PRAME were increased in tumor samples." (PMID 37728703, 2023). "In vitro, knockdown of Circ-TFF1 blocked BC cell growth, invasion, migration, and EMT while in vivo limiting tumor proliferation." (PMID 36157217, 2022). "Through the integrative analysis, it was observed that TFF1 and TFF2 were low expressed in tumor specimens, and their mRNA expressions were negatively associated with the DNA methylation level." (PMID 36428568, 2022). "The expression of genes encoding mucins (MUC1, MUC2 and MUC5A) or involved in mucosa protection (TFF1 and TFF3) were positively correlated with AGR2 expression in most tumour types." (PMID 35857928, 2022). "Our group identified trefoil factor family peptide 1 (TFF1) as a putative new RB marker correlating with higher clinical tumor-node-metastasis (TNM) stage and poorly differentiated tumor cells." (PMID 35158945, 2022). "The lower expression levels of TFF1 and TFF2 were observed in GC tumor tissues as compared to those in normal tissues." (PMID 36428568, 2022). "Taken together, these results suggest that TFF1 acts as a tumor suppressor during L1-mediated tumorigenesis and that its downregulation in CRC cells is a necessary step for tumor progression conferred by L1." (PMID 36139637, 2022). "(C) Violin plots of single-cell sequencing data showing expression levels of Gkn1, Tff1, Tff2, Cym, Pgc, Pga5, and Pou2f3 transcripts in BPN tumor clusters 1–3 and highlighting key drug-mediated cell-identity changes." (PMID 33821796, 2021). "M434 captures a tumor suppressive axis TFF1‐TFF2‐GKN1‐GKN2, where TFF2, GKN1/2 are found in M434, and TFF1 is found at a neighboring module directly connected to M434." (PMID 31463974, 2020). "Conversely, the tumor incidence in LSL-hMYH9; Atp4b-cre; Tff1-/- mice was significantly enhanced (16/20, 80%) and the tumor size was larger, when compared with LSL-hMYH9; Tff1-/- mice (9/20, 45%)." (PMID 32685004, 2020). "Detection of TFF1 and TFF3 mRNAs in peripheral blood has been proposed as a surrogate measure of circulating tumor cells." (PMID 28687783, 2017). "The TFF1 and TFF3 genes have been poorly studied regarding detection of circulating tumor cells in cancer patients." (PMID 24058517, 2013). "The expression of SERPINA, TFF1, CCNB1 and CDC2 were also measured by qRT-PCR in 42 of the tumour samples assayed by microarray." (PMID 20646288, 2010). "The qRT-PCR results revealed pronounced upregulation of TFF1, ITPKA, UBE2C, and IGFBP3, along with marked downregulation of SLC34A2 and SELENBP1 in tumor samples relative to adjacent normal tissues, which was in strong agreement with the transcriptomic profiling outcomes." (PMID 40787454, 2025). "One patient’s tumor (T4) was classified as RB subtype 1 without TFF1 expression and invasion of the choroid or optic nerve." (PMID 39695086, 2024). "Real-Time PCR analyses revealed that cultured primary RB patient-derived tumor cells, which do not express TFF1 (TFF1-negative; TFF1) displayed similar GIPR levels to healthy human retina (hRet)." (PMID 38730608, 2024). "Among 7870 tumor samples with available TFF1 and MUC5AC data, 573 (7.3%) showed expression of both TFF1 and MUC5AC, 1391 (17.7%) showed expression of only TFF1, 325 (4.1%) showed expression of only MUC5AC, and 5581 (70.9%) showed expression of none of the two proteins (p < 0.0001)." (PMID 39410561, 2024).
tumor (continued). "We confirmed that tamoxifen treatment did not affect tumor burden in Tff1:CreERT2 transgene-negative Gp130FF mice." (PMID 37957015, 2024). "TFF1 expression was, thus, evaluated in more than 18,000 tumor tissue samples from 149 different tumor types and subtypes as well as 76 different non-neoplastic tissue types by IHC in a tissue microarray (TMA) format in this study." (PMID 39410561, 2024). "One patient’s tumor (T7) presented a partial TFF1 expression in immunohistochemically staining, without TFF1 secretion into the aqueous humor, and no invasion into the choroid or optic nerve." (PMID 39695086, 2024). "Crucially, our data confirmed that TFF1-secreting cells within the tumor mass originate from RB tumor cells, not from surrounding stromal cells." (PMID 37835522, 2023). "Specifically, primary RB tumor cells exhibited high levels of TFF1 expression, while the corresponding RB-derived stromal cells showed no detectable TFF1 expression." (PMID 37835522, 2023). "We were able to demonstrate that only RB tumor cells and not RB-derived stromal cells express and secrete TFF1, rendering TFF1 a specific marker for RB tumor cells." (PMID 37835522, 2023). "Tumor expression of ER target genes progesterone receptor (PR), growth-regulating estrogen receptor binding 1 (GREB1), and trefoil factor 1 (TFF1/pS2) were all significantly elevated in E2-treated HFD- versus LFD-fed females." (PMID 37608351, 2023). "TFF1 expression in most of the corresponding primary cell cultures reflects the levels of the original tumor, although not all TFF1-expressing tumor cells seem to secret into the AH." (PMID 35158945, 2022). "To verify if IFNγ was directly involved in TFF1 silencing, we used the recombinant cytokine on KATO III, a tumour cell line that expresses high levels of the gastrointestinal protein, and confirmed that the treatment with the pro-inflammatory cytokine reduces both mRNA and protein levels of TFF1." (PMID 36514982, 2022). "In group III, without detectable TFF1 in AH samples, TFF1 probably is not secreted into the AH even if the tumor bulk contained TFF1-expressing cells detectable by immunohistochemistry." (PMID 35158945, 2022). "This scenario may activate oncogenic pathways (NF-κB, AP-1, PI3K, STAT3, Wnt/β-catenin, COX2 etc.) and silence tumour-suppressor genes (E-cadherin, RASSF1A, p16, GSTP1, SOCS1, SFRP1, PTEN, TFF1)." (PMID 36514982, 2022). "All patients with TFF1-positive AH also expressed TFF1 in the original tumor, whereas some RB tumors express TFF1 without secreting it into the AH." (PMID 35158945, 2022). "The potential of TFF1 to act as a tumor suppressor in L1-mediated CRC development is supported by our findings, which suggest that increasing TFF1 expression in L1-transfected CRC cells results in the inhibition of CRC cell proliferation, motility, tumorigenesis, and liver metastasis." (PMID 36139637, 2022). "Recently, we have shown the great potential of TFF1 expression downregulation, one of the genes epigenetically deregulated, as an early ESCC detection biomarker, since it takes place in the tumor-surrounding tissue from ESCC patients, preceding the first morphological and genetic alterations." (PMID 34422669, 2021). "To further validate the expression of the metaplastic markers in human samples, we stained human PDAC and adjacent tumor sections and could detect TGFB1 and TFF1 in lesions and tumors." (PMID 32908137, 2020). "TFF1 promoter was hypermethylated in tumor and histologically normal tumor surrounding tissue in comparison with healthy esophagus." (PMID 29296124, 2017). "Differential expression analysis between ER-positive and -negative tumours revealed that all three alternatively-spliced mRNA transcripts of ESR1 are (with TFF1) represented in the top four differentially-expressed genes." (PMID 28697743, 2017).